MMP1 (matrix metallopeptidase 1)
Diseases named in the same sentence as MMP1 in open-access papers (continued):
Sharing a sentence is not in itself a finding about the gene and the disease.
liver fibrosis (continued). "MMP-1/TIMP-1 ratio is useful for the diagnosis of hepatic fibrosis and correlates with degree of portal inflammation." (PMID 29255622, 2018). "In liver fibrosis, there will be inverse correlation between levels of MMP-1 and histological severity." (PMID 29255622, 2018). "The present authors’ group attempted to observe gene expression of MMP-1 in the process of hepatic fibrosis in rats treated with CCl4 for 12 weeks as well as in the recovery phase, 2, 5 and 7 days after the last injection." (PMID 24978432, 2014). "Moreover, MMP-1 is essential for the breakdown of ECM while experimental liver fibrosis is recovering." (PMID 39290493, 2024). "Indeed, MMP-1 mRNA was increased in liver tissue in cases with severe liver fibrosis or cirrhosis patients." (PMID 38111317, 2024). "They suggested that BMSCs may be a potential cell source in preventing liver fibrosis and MMP1 gene may enhance the anti-fibrotic effect of BMSCs." (PMID 34055009, 2021). "SREBP1c elevated PPARγ and MMP1 protein levels in the model of liver fibrosis." (PMID 32678475, 2020). "MMP-1 plays an important role in the regression of liver fibrosis in rodents." (PMID 32664553, 2020). "After UA treatment, this increase in the expression of type I collagen and TIMP-1 decreased, and the expression of MMP-1, an anti-fibrotic factor that promotes the degradation of extracellular matrix, was elevated, demonstrating that UV exerts a reversal effect on liver fibrosis." (PMID 32496208, 2020). "In addition, it was reported that MMP1 overexpression could suppress Thioacetamide (TAA)-induced liver fibrosis in rat model." (PMID 32478052, 2020). "Therefore, an improved understanding of the regulation of MMP-1/-13 activity in physiological and pathological conditions could lead to novel therapeutic interventions for liver fibrosis." (PMID 27412967, 2016). "However, we have previously reported that stem cells derived from bone marrow changed their phenotypes of MMP-13 (a major interstitial collagenase in rodents with homology to human MMP-1) to MMP-9 expression in the recovery phase from experimental liver fibrosis and cirrhosis." (PMID 24978432, 2014). "In animal studies, transient overexpression of MMP-1, which is capable of degrading collagen types I and III—the primary collagens in irreversible scar tissue—has been shown to effectively reduce hepatic fibrosis and promote hepatocyte proliferation." (PMID 40572790, 2025). "Diverse MMPs can degrade fibrillar-type collagen, as in liver fibrosis, but MMP-8, MMP-1, and MMP-13 have proven to display the main activity." (PMID 37681859, 2023). "The consumption of gallic acid regulated hepatic fibrosis by regulating the mRNA levels of MMP-2 and tissue inhibitor of MMP-1 in carbon tetrachloride-induced liver injury mice." (PMID 37760047, 2023). "The serum levels of resistin, TGF-β1, MMP-1, TIMP-1, collagen IA1 and PDGF-BB, which are markers that are known to be involved in the process of hepatic fibrosis, were assayed." (PMID 35715541, 2022). "The results showed that FA inhibited the proliferation and migration of LX2 cells and adjusted the expression of MMP-1, TIMP-1, COLI, α-SMA, TNF-α, IL-6 and IL-1β as well as promoted collagen metabolism to show potential in anti-hepatic fibrosis." (PMID 35035671, 2022). "TGF-β1 can induce TIMP-1 expression after signaling to Smad3, while inhibiting MMP-1 expression, making the ratio of TIMP-1 to MMP-1 increase, and promoting liver fibrosis." (PMID 35529927, 2022). "Magnesium chenoursodeoxycholic acid (Mg-CUD) suppression increases MMP-2 and tissue inhibitor of MMP-1 mRNA expression, as well as levels of NF-κB, TNF-α, IL-6, and COX-2 in carbon tetrachloride-induced liver fibrosis in rats." (PMID 34220502, 2021). "Tissue inhibitor of metalloproteinase-1 (TIMP-1) has a specific inhibitory effect on MMP-1, which reduces the degradation of ECM by MMP-1 and leads to the development of liver fibrosis." (PMID 34611503, 2021).
liver fibrosis (continued). "In both AAV- TβR1 therapy groups and in the combination therapy group, the expression levels of collagen I, collagen III, MMP1, TIMP1, TGF-β1, and TβR1 in the liver of rats with CCl4-induced hepatic fibrosis were significantly lower than in the model group." (PMID 34181670, 2021). "Based on results of network pharmacology, it was known that flavonoids can possibly suppress liver fibrosis by inhibiting the IL-17 signaling pathway, which includes NF-κB, AP-1, IL-6, IL-1β, TNFα, IFN-γ, CCL2, COX2, MMP1, MMP3, and MMP9." (PMID 33551818, 2020). "In contrast to these pro-fibrotic MMPs, animal models suggest that augmented levels of MMP1 decrease fibroplasia in liver, muscle and heart, while MMP2 decreased type I collagen production in experimental liver fibrosis." (PMID 32171287, 2020). "ELF is a commercially available panel that incorporates matrix turnover markers, such as matrix metalloproteinase 1 (MMP-1), HA, and amino-terminal propeptide of type III collagen level to predict liver fibrosis." (PMID 30889791, 2019). "Over expression of MMP-1, MMP-8 and MMP-13 was shown to reduce the number of activated HSC and attenuate the hepatic fibrosis when transiently over expressed in the liver." (PMID 30679661, 2019). "We believe that these results will provide important theoretical and experimental bases needed to control interstitial MMPs (MMP-1 in humans and MMP-13 in rats) and lead to the resolution of liver fibrosis." (PMID 27412967, 2016). "Several studies have reported a negative correlation between serum MMP-1 levels and the stage of hepatic fibrosis in chronic liver diseases." (PMID 40572790, 2025). "Furthermore, in our observations, MSC-CM was found to elevate the expression of MMP1, thereby promoting enhanced ECM degradation and rectifying the MMP1/TIMP1 imbalance, ultimately supporting liver fibrosis resolution." (PMID 38874773, 2024). "MMP-1 is a collagenase that degrade produced collagen, and the sustained inhibition of MMP-1 production by TIMP is a crucial mechanism in the pathogenesis of liver fibrosis." (PMID 39316687, 2024). "Furthermore, the OEFL and its main bioactive substance, p-coumaric acid, alleviated liver fibrosis by downregulating TGF-β, SMAD-2, SMAD-4, α-SMA, and upregulating MMP-1." (PMID 35208964, 2022). "Hepatic protein levels of TGF-β1, known for pro-fibrogenic cytokine to promote HSCs activation or proliferation were drastically normalized by GF and other proteins such as TIMP-1, MMP-1, and MMP-13 which are known as ECMs promoters or degradations as responses of liver fibrosis." (PMID 34829709, 2021). "MMP1 may have a role in the progression of NAFLD to NASH and then to liver fibrosis." (PMID 34988225, 2021). "BMSCs/MMP-1 treatment resulted in decreased collagen levels and attenuated HSCs activation in fibrotic livers, subsequently resulting in amelioration of liver injury and fibrosis, indicating BMSCs/MMP-1 as a potential antifibrotic approach for the resolution of liver fibrosis." (PMID 32414178, 2020). "Indeed, we focused on the proteases involved in the degradation or modification of ECM (MMP-1 and TIMP-1), the products of ECM (collagen IA1) and fibrosis-related regulatory factors, such as PDGF-BB, TGF-β1, and resistin, all of whose essential roles in liver fibrosis have been established." (PMID 35715541, 2022). "MMP-1 and TIMP-1 are closely related to liver fibrosis, however, we do not know their role in early stage of liver fibrosis such as chronic hepatitis or even acute hepatitis." (PMID 34611503, 2021). "Recent in vitro cytology studies have shown that tanshinone IIA can inhibit TIMP-1 expression and increase MMP-1 expression in HSCs, but whether tanshinone IIA can affect liver fibrosis by regulating MMPs and TIMPs in vivo in liver tissue has not been reported in relevant animal experiments." (PMID 31915451, 2019).
ovarian carcinoma (53 papers, 2008 to 2025). A malignant neoplasm originating from the surface ovarian epithelium. "In this study, both ST09 treated ovarian cancer cell lines showed downregulation of MMP1, MMP2, and MMP9 with DDR1 loss." (PMID 34837026, 2021). "Matrix Metalloproteinase-1 (MMP1) expression in ovarian cancer is linked with poor prognosis and was found to be packaged into EVs and transferred to the mesothelial cells." (PMID 30682793, 2019). "Highly metastatic cancers, like ovarian cancer, secrete EVs carrying mRNA encoding for matrix metallopeptidase 1 (MMP1), which strongly induces metastatic behavior in moderately metastatic tumors." (PMID 31795140, 2019). "The presence of a MMP-1 1G/2G polymorphism in the promoter region of the MMP-1 gene is positively correlated with an increased risk for developing various types of cancer such as lung or ovarian cancer." (PMID 25625008, 2014). "Accordingly, the 2G allele of the MMP1 1G/2G polymorphism has been associated with worse survival among patients with colorectal and ovarian cancer." (PMID 19094243, 2008). "Furthermore, in colorectal and ovarian cancer, the presence of the 2G allele in the MMP1 gene was significantly associated with poorer survival of patients with cancer." (PMID 19094243, 2008). "Clinically, elevated serum MMP-1 has been identified as an independent poor prognostic factor in ovarian cancer patients." (PMID 41296178, 2025). "This study identified MMP1 as a central hub gene in cisplatin resistance in epithelial ovarian cancer (EOC)." (PMID 40535817, 2025). "Summary of preclinical studies carried out with PZ‐128 and the MMP1 Inhibitor in breast, lung, and ovarian cancer." (PMID 40969301, 2025). "MMP-1 and MMP-13 have shown preliminary potential in the biochemical diagnosis of ovarian carcinoma—as diagnostic markers (in stand-alone or combined assays) and as auxiliary differentiation markers assayed together with the ROMA." (PMID 39682156, 2024). "Most of the tested metalloproteinases upregulated mRNA expression in both FIGO I/II and FIGO III/IV stages of ovarian cancer (MMP1, MMP13, MMP2, MMP9, MMP10, MMP7, MMP12 and MMP14) indicating profound modifications of the extracellular matrix." (PMID 38397798, 2024). "As MMP1 plays a significant role in invasion of cancer cells through extracellular matrix, its down regulation in ovarian cancer cells accounts for the anti-metastatic potential of omentin-1." (PMID 34588926, 2021). "Highly metastatic ovarian cancer cells secrete EVs with high concentrations of MMP1 mRNA and are transferred to mesothelial cells, the most prevalent cells in the peritoneal cavity." (PMID 34527665, 2021). "By inhibiting LTF binding with its receptor LRP-1 (low intensity lipoprotein receptor related protein 1), omentin-1 attenuates the upregulation of MMP1 in ovarian cancer cells." (PMID 34588926, 2021). "MMP1 and MMP7 are well-known metalloproteinases to facilitate metastasis and peritoneal dissemination in ovarian cancer, and their overexpression is linked to advanced cancer stages and poor prognosis." (PMID 32823589, 2020). "Exosomal MMP1 mRNAs loaded in ovarian cancer-derived exosomes induce apoptotic changes in PMCs and disrupt the peritoneal mesothelial barrier, promoting the invasion of ovarian cancer cells." (PMID 32230983, 2020). "Further studies demonstrate that ITLN1 suppresses lactotransferrin’s effect on ovarian cancer cell invasion potential and proliferation by decreasing MMP1 expression and inducing a metabolic shift in metastatic ovarian cancer cells." (PMID 32669559, 2020). "MMP1-protease-activated receptor-1 (PAR1)-CXCR1/2 paracrine pathways have been suggested as new targets for ovarian cancer therapy involving peritoneal metastasis." (PMID 32780245, 2020). "For example, MMP2 and MMP14 production is stimulated by the ovarian cancer cells while that of MMP1 is enhanced by the gastric cancer cells." (PMID 32780245, 2020).
ovarian carcinoma (continued). "First, MMP1 mRNA has been found in extracellular vesicles derived from ovarian cancer cell lines and ascites from ovarian cancer patients that promotes apoptotic cell death of the mesothelial cells, thus resulting in the destruction of the peritoneal barrier." (PMID 31614568, 2019). "In their study, they found that MMP1 mRNA in EVs from ovarian cancer-induced apoptosis in mesothelial cells, leading to the peritoneal metastasis of ovarian cancer cells." (PMID 30872565, 2019). "In this report, it was shown that the expression level of MMP1 mRNA from ovarian cancer patient ascites is higher than that in healthy donors." (PMID 31447954, 2019). "For example, ARG2 and MMP1 expression have been found to correlate with poor prognosis in gastric and ovarian cancer, respectively." (PMID 30416686, 2018). "MMP-1 is also regulated by mixed lineage kinase 3 (MLK3) which is expressed at high levels in ovarian cancer cells." (PMID 29393911, 2018). "MMP-1 expression in ovarian cancer cell lines also requires other regulators, such as mixed lineage kinase 3 (MLK3)." (PMID 28538838, 2017). "Approximately 30% of ovarian cancer tissues expressed high levels of MMP1 in 594 samples from The Cancer Genome Atlas database." (PMID 28262727, 2017). "A phase I study of Marimastat (MMP-1, 2, 7, 9 and 14 inhibitor) plus carboplatin was performed in patients with ovarian cancer who previously responded to a platinum-based regimen, and the drug was tolerated well (Thomas, H 1997)." (PMID 27072580, 2016). "Particularly noteworthy is the fact that activation of G-protein-coupled receptor protease-activated receptor-1 (PAR1) by matrix metalloproteinase (MMP1) is a principal promoter of angiogenesis and metastasis in peritoneal mouse models of ovarian cancer." (PMID 22481932, 2012). "In addition, exosomes secreted by ovarian cancer containing matrix metallopeptidase 1 (MMP1) mRNAs induce peritoneal mesothelial cells to undergo apoptotic cell death, thereby promoting peritoneal cancer metastasis." (PMID 36361760, 2022). "Expression of MMP1 in ovarian cancer tissues correlates with poor prognosis." (PMID 34907282, 2021). "LPA induced increased expression of MMP-1, also known as interstitial collagenase, in ovarian cancer cells have been correlated with increased invasion of cancer cells and has been shown to be mediated by the G-protein coupled receptor, protease-activated receptor-1(PAR1)." (PMID 29393911, 2018). "To test this hypothesis, we first examined the expression of MMP1 in ovarian cancer, to determine its clinical relevance." (PMID 28262727, 2017). "Among these studies, 8 studies with 2 polymorphisms (5 studies for MMP1 rs1799750, 3 studies for MMP3 rs34093618) involving 1019 ovarian cancer cases and 1609 controls could be quantitatively synthesized for meta-analysis." (PMID 28957437, 2017). "Given that the EVs carrying MMP1 mRNAs contributed to peritoneal dissemination in ovarian cancer, the MMP1 expression levels could be a useful and critical marker of prognosis in ovarian cancer patients." (PMID 28262727, 2017). "Our transcriptome analysis of miR21-transfected ovarian cancer cells showed upregulation of MMP1, which may lead to an increase in the invasion potential of ovarian cancer cells, as we observed in our in vitro studies." (PMID 27021436, 2016). "These EVs contained high levels of MMP1 mRNA that induced apoptosis in mesothelial cells MMP1 expression levels in EVs from ascites fluid were strongly related to patient prognosis in early stages of ovarian cancer and thus are a promising biomarker for the degree of ovarian cancer malignancy." (PMID 34527665, 2021). "Importantly, MMP1 expression in ovarian cancer is tightly correlated with a poor prognosis." (PMID 28262727, 2017). "Thus, MMP1 in EVs could be a prognostic biomarker, because the MMP1 expression level in tumour tissues is strongly related to prognosis in stage l ovarian cancer patients." (PMID 28262727, 2017).
ovarian carcinoma (continued). "In conclusion, collagenases MMP-1 and MMP-13 show bidirectional potential in the biochemical diagnosis of ovarian cancer." (PMID 39682156, 2024). "While it has been reported that the CELF2/FAM198B axis regulates proliferation and metastasis in ovarian cancer, FAM198B was also shown to prolong survival and inhibit metastasis in lung adenocarcinoma by blocking ERK-mediated MMP-1 expression." (PMID 35587159, 2022). "Consistent with this transcriptomic observation, proteomics identified that KIT was attenuated, whereas MMP1 and MMP7 were elevated in CD83-KD ovarian cancer cells." (PMID 32823589, 2020). "Using an integrated analysis of proteomic and transcriptomic data, we have observed the positive regulation of proliferation/stemness factors (e.g., cyclins-CDKs and KIT) and negative regulation of MMPs (e.g., MMP1 and MMP7) by CD83 in ovarian cancer cells." (PMID 32823589, 2020). "Accordingly, Axl knockdown in ovarian cancer SKOV3 cells has been shown to reduce PI3K/Akt activation and the expression of MMP-1 and MMP-9, both in vitro and in vivo using the peritoneal xenograft model of ovarian cancer." (PMID 26356564, 2015). "ETS1 is found to be co-expressed with MMP-1 and MMP-9 in angiosarcoma of the skin, ovarial carcinoma cells and stromal fibroblasts in breast and ovarian cancer." (PMID 26177288, 2015). "In this module, 5 genes (FN1, MMP2, MMP1, PLAU, and SPARC), colored in green, were identified as ovarian cancer-related genes in the DDOC database." (PMID 25611546, 2015). "AXL protein expression was found to be significantly higher in ovarian carcinomas than in ovarian epithelium, and knockdown of AXL in SKOV3 cells also reduced the expression of MMP-1 and MMP-9, which contribute to tumour cell invasion." (PMID 23878800, 2013). "FAM198B may act to favor tumor progression by interacting with numerous genes, such as the p-ERK/MMP-1 signaling pathway in lung adenocarcinoma, and S100A3, PCDH9, and SEMA3A genes in ovarian cancer." (PMID 35587159, 2022). "In ovarian cancer, noncanonical MMP1-medited PAR1 activation was critical in regulating chemokine signaling." (PMID 30065181, 2018). "Additionally, AXL has been shown to regulate MMP-1, MMP-2 and MMP-9 expression in ovarian cancer." (PMID 27764792, 2016).